ALB (albumin)
Diseases named in the same sentence as ALB in open-access papers (continued):
Sharing a sentence is not in itself a finding about the gene and the disease.
gynecological cancer (13 papers, 2010 to 2025). "Numerous studies have highlighted that low albumin levels are prevalent among gynecologic cancer patients and are often linked to poorer prognosis, increased postoperative complications, and reduced overall survival rates." (PMID 39529928, 2024). "The high percentage of urine albumin to total protein and high sensitivity of the simple UD test for detecting macroalbuminuria suggested that using the simple UD test to screen gynecologic cancer patients at risk of bevacizumab-associated proteinuria might be beneficial." (PMID 39272637, 2024). "Fibrinogen-to-albumin ratio (FAR) has been widely studied for its prognostic value in gynecological cancers, but the results remain inconsistent." (PMID 40678069, 2025). "This study evaluated the nutritional status of Chinese gynecologic cancer survivors experiencing LLL by analyzing serum albumin levels and PNI." (PMID 39529928, 2024). "This study aims to evaluate the nutritional status of Chinese gynecologic cancer survivors with post-surgical lower limb lymphedema (LLL) by analyzing serum albumin levels and the prognostic nutritional index (PNI)." (PMID 39529928, 2024). "As a result, increased CONUT scores, which are the result of decreased serum ALB, lymphocytes, and cholesterol levels, are a reasonable indicator of poor survival in patients with gynecological cancer." (PMID 37422623, 2023). "Various factors including hemoglobin, total protein, albumin, and transferrin are used to evaluate the nutritional status in patients with gynecological cancer." (PMID 29193777, 2018). "Lyell used the preoperative serum albumin level as a biomarker to predict survival prognosis and the occurrence of any postoperative complications in patients receiving pelvic exenteration surgery in colorectal, genitourinary, and gynecologic cancer." (PMID 36558490, 2022). "In term of future perspectives on managing the nutritional status of gynecological cancer patients, elevating serum albumin level could be a primary focus." (PMID 35127741, 2021). "The 30-day morbidity after gynecologic cancer surgery could be predicted according to age, operation time, and serum albumin level." (PMID 28570652, 2017). "Low albumin levels could therefore be a consequence of systematic inflammatory response and malnutrition in advanced stage tumors; in line, albumin could be established as both predictive for therapy response and prognostic for survival in several gynecologic cancers." (PMID 36579608, 2022). "We aim to address the gap in the literature by evaluating the serum albumin and the PNI of patients who have undergone surgery for gynecological cancers and developed LLL." (PMID 39529928, 2024). "Given the high prevalence of low albumin and PNI among gynecologic cancer survivors with LLL, regular nutritional assessments should be integrated into their care plans." (PMID 39529928, 2024). "An inverse relation between serum albumin and LOS among patients with gynecological cancers has been documented." (PMID 36547125, 2022). "The results of our study confirmed previous findings by Massad and colleagues in which they found an inverse correlation between serum albumin and LOS among patients with gynecological cancer." (PMID 20497581, 2010). "In the previously suggested models for gynecologic cancer, the serum albumin level had not been analyzed as a potential predictor for postoperative morbidity." (PMID 28570652, 2017).
Immunodeficiency (13 papers, 2005 to 2025). Failure of the immune system to protect the body adequately from infection, due to the absence or insufficiency of some component process or substance. "Total IgG and total albumin were low (IgG 1.57 g/l and albumin 20 g/l), indicating a secondary immune deficiency." (PMID 27224999, 2016). "This may be related to chronic blood loss and prolonged loss of albumin and globulin, resulting in decreased protein and immune deficiency in patients with hypoproteinemia." (PMID 34901161, 2021). "The immune response is directly affected by the nutrition status; thus, a decline in serum albumin leads to immunodeficiency of cell-mediated immunity for the host defenses against cancer." (PMID 33516219, 2021).
interstitial lung disease (13 papers, 2019 to 2026). A diverse group of lung diseases that affect the lung parenchyma. "Past steroid dose, underlying interstitial lung disease and emphysema, lower serum albumin and lower lymphocyte count, higher lactate dehydrogenase, use of therapeutic pentamidine and therapeutic high-dose steroids were all significantly associated with mortality." (PMID 38330061, 2024). "In the multivariate analysis, underweight based on new BMI (HR 5.285), age (HR 1.057), male sex (HR 3.595), BVAS (HR 1.161), FFS (HR 2.957), interstitial lung disease (HR 31.874), and serum albumin levels (HR 0.134) were independent predictors of all‐cause mortality." (PMID 35312104, 2022). "Smokers had increased ELF volume and decreased albumin levels, while ELF of patients with interstitial lung disease had increased albumin levels according to BAL measurements." (PMID 31284402, 2019). "In the univariate analysis, age, male sex, BVAS, FFS, interstitial lung disease, serum creatinine levels, serum albumin levels, C‐reactive protein (CRP) levels, and underweight based on the new BMI category at diagnosis were associated with all‐cause mortality during the follow‐up." (PMID 35312104, 2022).
oesophageal cancer (13 papers, 2009 to 2025). "A statistically significant association was only observed for oesophageal cancer in those with BMI < 25 kg/m2 [HR: 1.92 (95% CI: 1.32-2.82) for every SD increase in albumin-corrected calcium]." (PMID 23866097, 2013). "The Odds ratio (OR) of ADP, oxLDL, oxLDL-ab, oxLDL-lgG and oxLDL-lgM were associated with the different stages in the development of esophageal carcinoma (basal cell hyperplasia, dysplasia and early invasive cancer) after adjusted for age, albumin, TC, HDL and LDL." (PMID 19863824, 2009). "In 2015, Matsudaet al. first constructed the fibrinogen albumin (FA) score, representing a new assessment system for predicting the prognosis of patients with esophageal carcinoma based on the preoperative fibrinogen and albumin levels." (PMID 32257553, 2020). "A study on oesophageal cancers reported that albumin levels play an important role on prognosis as a general view, and suggests that preoperative nutrition support should be optimized in such patients." (PMID 26782276, 2016). "The prognostic relevance of albumin levels in esophageal carcinomas has been well documented." (PMID 39400724, 2024). "Whilst this study has validated pre-treatment dNLR as a potential prognostic biomarker for oesophageal cancer patients treated with dCRT, analysis of other haematological components, albumin and other markers of the systemic inflammatory response such as C-reactive protein (CRP) was not conducted." (PMID 28893415, 2017). "In this multivariate survival analysis on patients with oesophageal cancer, CRP/Albumin ratio >0.50 was shown to be related to a statistically significant worse overall survival (HR: 2.44 95% CI 1.82–3.26 p < 0.0001)." (PMID 29196718, 2017).
primary hyperparathyroidism (13 papers, 2014 to 2025). "Normocalcemic primary hyperparathyroidism is a variant of primary hyperparathyroidism with consistently normal albumin-adjusted or free-ionized calcium levels." (PMID 37065752, 2023). "Comparing the two variants of primary hyperparathyroidism, mean sCa levels were higher in PHPT (10.8 mg/dL) compared to NHPT (9.9 mg/dL), as were sCaMin and sCaMax, serum calcium corrected for albumin, and Ca/P ratio, as expected." (PMID 39963179, 2024). "We arbitrarily defined primary hyperparathyroidism as albumin-corrected total serum calcium ≥9.5 mg/dL (unsuppressed serum calcium with an elevated PTH level, n = 212), and secondary hyperparathyroidism as calcium <9.5 mg/dL (n = 237)." (PMID 25514572, 2014). "Moreover (to our knowledge), primary hyperparathyroidism does not cause serum albumin levels to decline." (PMID 32723677, 2020). "Studies reported decreased levels of DBP and albumin in patients with primary hyperparathyroidism and an inverse linear correlation between iPTH and DBP or albumin levels." (PMID 40362670, 2025). "Our aim was to provide an estimate of the least significant change for albumin-adjusted calcium in patients with normocalcaemic hyperparathyroidism (NPHPT) and primary hyperparathyroidism (PHPT)." (PMID 33112283, 2021).
proliferative diabetic retinopathy (13 papers, 2011 to 2025). Advanced retinopathy due to diabetes mellitus characterized by the formation of new vessels in the retina. "At the same time, our findings are in keeping with the greatest risk factors for proliferative diabetic retinopathy in the DCCT, including an elevated urinary albumin excretion rate and higher mean DBP." (PMID 35182158, 2022). "They emphasized that all patients with proliferative diabetic retinopathy should undergo an evaluation of renal function including urinary albumin measurements." (PMID 21612596, 2011). "Moreover, the retinal lesions of patients with proliferative diabetic retinopathy (PDR) associated with a loss of Tbdn expression and hyperpermeability to Albumin displayed increased levels of activated SFK in retinal blood vessels." (PMID 26142315, 2015).
psychosis (13 papers, 2014 to 2024). "Overall, we revealed that psychotic disorders are associated with increased CSF-to-serum albumin ratio, and increased blood S100B, MMP-9, and zonulin." (PMID 37692299, 2023). "The ‘gold standard’ of BBB quantification in humans is the CSF-serum albumin quotient, which has consistently been found to be abnormal in psychosis." (PMID 33077853, 2021). "Previous studies have reported CSF abnormalities in psychosis spectrum patients (e.g., elevated total protein concentration, and albumin ratio) and we first aimed to replicate these findings." (PMID 34363013, 2021). "The protein with the greatest fold-change was albumin, 3.2-fold and 4.1-fold in controls and psychosis patients, respectively." (PMID 29249827, 2017). "Lower albumin plasma levels were detected in high-risk psychotic subjects who converted to a condition of full-blown psychotic disorder compared to those who did not." (PMID 38541067, 2024). "In a previous study we detected increased albumin quotients in 21.8% of patients with psychosis." (PMID 28008318, 2016). "In addition, lower albumin plasma levels were detected in ultra-high-risk psychotic patients who converted to a condition of full-blown psychotic disorders with respect to those who did not; thus, this parameter could be monitored to predict the risk of psychotic disorders in vulnerable subjects." (PMID 38541067, 2024).
pulmonary fibrosis (13 papers, 2012 to 2025). Chronic progressive interstitial lung disorder characterized by the replacement of the lung tissue by connective tissue, leading to progressive dyspnea, respiratory failure, or right heart failure. "Our results showed that there were significant relationships between pulmonary fibrosis and the levels of albumin and IL-6, which suggests that IL-6 and albumin are independent risk factors affecting pulmonary fibrosis." (PMID 33755708, 2021). "The IL-6 level in the acute stage and albumin level were independent risk factors for pulmonary fibrosis." (PMID 33755708, 2021). "A total of 49 active ingredients were analyzed and screened in Cephalus cephalusis, including 35 pulmonary fibrosis targets, and 10 key targets such as ALB, EGFR were screened after software analysis." (PMID 37713849, 2023). "The use of Tween 80 to disperse FLG or a pluronic surfactant to disperse graphene was suggested to reduce the likelihood of lung fibrosis formation in cells or mice, whereas lung fibrosis was observed when graphene was suspended with bovine serum albumin (BSA)." (PMID 27799056, 2016). "As large amounts of cytokines and inflammatory medium were produced in the course of the ILD disease, which could lead to a decrease in hepatic albumin synthesis, pulmonary fibrosis could be activated and progressed because of the protective effect of albumin was diminished." (PMID 37382274, 2023). "Reduced serum ALB may increase active fibroblasts and aggravate pulmonary fibrosis." (PMID 37647425, 2023). "Our results show that engineered mannosylated albumin nanoparticles specifically targeted disease-inducing Mo-Macs, and further, that nanoparticles efficiently delivered small-interfering RNA against profibrotic cytokine tumor growth factor β1 to prevent bleomycin-induced lung fibrosis." (PMID 35377803, 2022). "The blood serum albumin (BSA) level decreased significantly in the BI group compared to the CI group at the end of the induction phase, reflecting the impact of pulmonary fibrosis and inflammation on protein metabolism and liver function." (PMID 40542974, 2025). "Mannosylated albumin nanoparticles incorporating TGFβ1 small-interfering RNA (siRNA) targeted the profibrotic subpopulation of CD206+ macrophages and prevented lung fibrosis." (PMID 35377803, 2022).
rheumatic diseases (13 papers, 2018 to 2024). "Characteristics of the studies investigating ischemia‐modified albumin in patients with rheumatic diseases and healthy controls." (PMID 38888377, 2024). "Our study suggests that ischemia‐modified albumin is a promising biomarker of oxidative stress, acidosis, and ischemia in different types of rheumatic diseases." (PMID 38888377, 2024). "All this evidence supports the possibility of including serum ALB measurement in such a composite score range to better and easily stratify patients and improve their outcomes in rheumatic diseases." (PMID 37762957, 2023). "Gamma gap is the difference in total serum proteins and albumin and an elevated gamma gap is related to infections, malignancy, and rheumatic diseases." (PMID 29416697, 2018). "Rheumatic diseases may involve multiple systems, including the liver, which can be damaged and result in a reduction in albumin synthesis.It is worth noting that albumin levels decrease as the infection progresses and are linked to inflammatory response and organ failure." (PMID 37908850, 2023). "Recent works in the scientific literature reported the role of C reactive protein to albumin ratio (CAR), neutrophil to lymphocyte ratio (NLR) and platelet to lymphocyte ratio (PLR) as biomarkers of disease activity in rheumatic diseases." (PMID 38886765, 2024). "The important characteristics of rheumatic diseases are inflammation response and immune disorder, which can be aggravated by infection, resulting in increased RDW and decreased albumin levels in the body." (PMID 37908850, 2023). "Albumin, thrombocyte count, and ferritin are other tests that clinicians should consider when caring for a patient with ESR ≥ 100 mm/h who has rheumatic disease." (PMID 36945971, 2022).
schistosomiasis (13 papers, 2012 to 2025). An infectious disease caused by parasitic trematodes of the genus Schistosoma that colonize human blood vessels and release eggs that can cause granulomatous reactions leading to acute (swimmer's itch or acute schistosomiasis syndrome) or chronic disease. "Similar to frequency of ascites, ALB level is also important to longer-term survival in advanced schistosomiasis in our study." (PMID 40424464, 2025). "This suggests that detecting and promptly correcting albumin levels are essential for patients with advanced schistosomiasis." (PMID 40424464, 2025). "We found that TBA, AST and ALB better reflected the different stages of schistosomiasis than levels of bilirubin." (PMID 39212529, 2024). "Serum levels of albumin are an important indicator of liver damage, which were significantly lower in patients with severe schistosomiasis." (PMID 35493725, 2022). "Even though the statistic was not significant in multivariate Cox regression analysis (P = 0.055), the further study of the ALB role in survival outcome of patients with advanced schistosomiasis was essential." (PMID 32375846, 2020). "Their blood pressure was measured, urine examined via dipstick and albumin/creatinine ratio and blood drawn for creatinine, cystatin C and sero-markers for schistosomiasis." (PMID 27875991, 2016). "Severe schistosomiasis patients present with abnormal portal vein diameter (PVD) ≥ 13 mm, elevated AST and HA levels, lower levels of albumin, and higher ascites grade." (PMID 35493725, 2022). "Study on combining Zithromax with ALB and IVM is also underway in Mali, which will pave the way for further combination in non-schistosomiasis MDA areas." (PMID 22448294, 2012). "As the diseased liver in schistosomiasis largely preserves hepatocyte architecture and synthetic capacity, it is perhaps not surprising that albumin levels were unchanged." (PMID 26267788, 2015). "As a total group, the patients with hepatosplenic schistosomiasis showed abnormal liver function tests compared to the healthy controls with significantly (p<0.05) increased levels of serum AST, ALT, γ-GT, ALP and total bilirubin, and a lower concentration of albumin." (PMID 23875049, 2013).
soft tissue sarcoma (13 papers, 2010 to 2025). A malignant neoplasm arising from muscle tissue, adipose tissue, blood vessels, fibrous tissue, or other supportive tissues excluding the bones. "Previous studies have also proved that serum albumin could be used for individual risk estimation and integrated in existing prognostic models for soft tissue sarcoma." (PMID 38188302, 2023). "The aim of the present study is to evaluate the prognostic value of the preoperative fibrinogen/albumin ratio (FAR) in surgical patients with soft tissue sarcoma (STS) and to compare this value with other inflammatory biomarkers." (PMID 30285656, 2018). "A study analyzing a group of 61 patients with soft tissue sarcomas found advanced stage, high tumor grade, irresecability, and serum albumin as independent prognostic factors of survival upon multivariate analysis." (PMID 21176210, 2010). "Data on individual co-morbidities may not be completely captured and other inflammatory markers known to be prognostic in soft tissue sarcoma, such as CRP, ESR or albumin were also unavailable." (PMID 30097600, 2018).